FRZB (frizzled related protein)
Diseases named in the same sentence as FRZB in open-access papers (continued):
Sharing a sentence is not in itself a finding about the gene and the disease.
tumor (continued). "Another potential tumor suppressor upregulated in topotecan-resistant patients is SFRP1, a member of the secreted frizzled-related protein (SFRP) gene family that shares sequence homology with Fzd receptors, can sequester Wnt ligands and antagonize Wnt signaling." (PMID 31195594, 2019). "However, a closer look at the respective genes reveals that many of them (SFRP5, WISP3, DKK4, FRZB and JUP) are antagonists of the 'WNT-beta catenin' pathway, thus exerting a tumor suppressor role in normal conditions." (PMID 19327144, 2009). "As downregulation of secreted Frizzled-related protein (sFRP) has been reported to be tumour-related, we did not further characterise this gene." (PMID 14997212, 2004). "One of them, SFRP2, is a member of the secreted frizzled-related protein (SFRP) family and a typical regulatory protein of the WNT pathway; it has been reported as a co-factor for ten-eleven translocation 1 (TET1), contributing to the inhibition of tumor metastasis." (PMID 38069266, 2023). "Interestingly, we observe that non-diseased bladder epithelium exhibits a similar extent of methylation at HOXB2 and KRT13 as the non-invasive disease, while at FRZB the non-diseased tissue has a significantly lower extent of methylation than either of the 2 tumor types." (PMID 20808801, 2010). "Nim-NPs inhibit Wnt/β-catenin signaling by downregulating DNA methyltransferases, thus epigenetically restoring the expression of the secreted frizzled-related protein 1 (SFRP1) and resulting in tumor growth and metastasis formation inhibition without systemic toxicity." (PMID 39065798, 2024).
cancer (26 papers, 2009 to 2025). A tumor composed of atypical neoplastic, often pleomorphic cells that invade other tissues. "Frizzled relatedprotein (FRZB) has been reported in many inflammatory diseases and cancers, butit is yet unclear how FRZB affects HNSCC, as well as its role and underlyingmechanism." (PMID 38775547, 2024). "Through this key regulatory function, FRZB has been found as an important oncogene that initiates metastatic properties in human cancers." (PMID 30602942, 2018). "The secreted frizzled-related protein (SFRP) family plays a significant role in the inhibition of the Wnt signaling pathway in various cancers." (PMID 24591760, 2014). "The frizzled-related protein (SFRP3) is generally thought to be an inhibitor of Wnt signaling in several cancers." (PMID 24591760, 2014). "Frizzled-related protein, which functions as an antagonist of the Wnt pathway, exerts inhibitory effects on the epithelial-mesenchymal transition or migration activity in several cancers, including lung cancer." (PMID 31061410, 2019). "The expression of FRZB was positively correlated withmost immune cells, such as NK cells (r=0.332, P<0.001), B cells (r=0.503,P<0.001), regulatory T cells (Tregs) (r=0.302, P<0.001), CD8+ T cells(r=0.440, P<0.001), cancer-associated fibroblast (r=0.308, P<0.001), andCD4+ T cells (r=0.460, P<0.001)." (PMID 38775547, 2024). "Frizzled related protein (FRZB), also known as secreted frizzled-related protein 3 (SFRP3), is manifested to involve in cancer development." (PMID 34364402, 2021). "Here, we report a previously uncharacterized mechanism by which Rab37 mediates exocytosis of secreted frizzled-related protein-1 (SFRP1), an extracellular antagonist of Wnt, to suppress Wnt signaling and cancer stemness in vitro and in vivo." (PMID 30158579, 2018). "First, four out of 16 representative DEGs found in all three subtypes of canine MGTs have strong references in human cancer as biomarkers: CCL23, CXCL10, SFRP2, and FRZB." (PMID 30205506, 2018). "Here, we report a novel anti-cancer stemness function of Rab37, which mediates secreted frizzled-related protein-1 (SFRP1), an extracellular antagonist of Wnt19–21, for exocytosis to suppress cancer stemness." (PMID 30158579, 2018). "Two members of the secreted frizzled-related protein (SFRP) family, SFRP1 and SFRP4, were more frequently down-regulated in MSI-positive carcinomas compared with MSI-negative carcinomas." (PMID 20368795, 2010). "According to the results, we found that the expression of FRZB was obviouslydownregulated in multiple cancers including HNSCC compared to samples of non-tumortissues." (PMID 38775547, 2024). "In addition, several of these genes have not previously been reported as methylated in any type of cancer (KCNK4, SEPT5, PENK, BMP4, TAL1, PGF, SMARCB1 (INI1), FRZB (SFRP3), IRAK3 and MCM2)." (PMID 19493342, 2009).
cardiovascular disease (2 papers, 2020 to 2023). "NPPA, NPPB and FRZB are recognized as biomarkers for HF,20, 21 and PLA2G2A is a biomarker for cardiovascular disease." (PMID 32638546, 2020).
myopathy (1 paper, 2020). A disease of the muscle in which the muscle fibers do not function properly. "Trace FRZB immunoreactivity was seen in two patients with myopathy (Myo1, necrotizing myopathy) and inflammatory; Myo2, inflammatory myopathy)." (PMID 33028902, 2020). "Whether it is a general marker of muscle denervation remains to be seen since there was modest detection of FRZB expression in myopathy samples." (PMID 33028902, 2020). "Taken together, these findings show a significant increase of FRZB in ALS muscle samples compared to normal and myopathy controls." (PMID 33028902, 2020).
FRZB also shares sentences with these, for which no sentence is quoted: alveolar rhabdomyosarcoma (3 papers); colon carcinoma (3); Hypertension (3); keratoconus (3); prostate carcinoma (3); ampullary adenocarcinoma (2); astrocytomas (2); Chronic Heart Failure (2); Cirrhosis (2); diabetes (2); Graves disease (2); medulloblastoma (2); myocardial infarction (2); ovarian carcinoma (2); prostate tumor (2); Type 2 diabetes (2); viral infection (2); acute coronary syndrome (1); adenoma (1); Alzheimer disease (1); Anxiety (1); asthma (1); atrial fibrillation (1); Atrophy (1); Barrett esophagus (1); brain disorder (1); brain tumors (1); cardiac hypertrophy (1); cervical cancer (1); chronic hepatitis (1).
A further 42 diseases each share a sentence with FRZB in 1 paper.